SYT14P1 (synaptotagmin 14 pseudogene 1)
Description:
Plays a role in melanocyte differentiation; enhances dendrite outgrowth, melanin content and tyrosinase activity through the modulation of ERK and/or CREB pathways.
Synonyms: SYTDEP; CHR415SYT; formerly SYT14L
Gene: Transcribed processed pseudogene on chromosome 4 (68,062,548 to 68,063,268, reverse strand). Ensembl gene ENSG00000215127.